CHEK2 (checkpoint kinase 2)
Diseases named in the same sentence as CHEK2 in open-access papers (continued):
Sharing a sentence is not in itself a finding about the gene and the disease.
breast cancer (continued). "CHEK2 germline pathogenic variants are identified at a relatively high frequency among hereditary breast cancer cases and are known to be associated with intermediate breast cancer risk i.e., 2–2.5-fold increase, compared to the general population." (PMID 33925588, 2021). "Also the c.470T>C (p.I157T) mutation in CHEK2 in the patient’s tumor has been widely studied by us and other in breast cancer predisposition in Finland and elsewhere." (PMID 34084283, 2021). "Based on the evidence available for CHEK2 mutations in breast cancer, this variant might be involved in the mother’s breast cancer." (PMID 34771502, 2021). "On the other hand, this founder mutation has not been observed in Japanese individuals, resulting in the number of patients with pathogenic variants in CHEK2 in European populations (1.12% of breast cancer patients) to be threefold higher than in the Japanese population (0.38%)." (PMID 32948841, 2021). "The testing of the 92-year-old grandmother and her 72-year-old daughter showed no pathogenic variants or VUSs, yet the tested 50-year-old grandson had CHEK2 (p.Arg145Trp) likely pathogenic variant, evidently from his paternal side as two of his paternal aunts had breast cancer." (PMID 33558524, 2021). "The CHEK2/1100delC, a truncating variant, is present in 13.5% of individuals from families with male breast cancer (p = 0.00015) and results in an approximately ten-fold increase of breast cancer risk in men." (PMID 33959510, 2021). "PALB2 and CHEK2 are clear breast cancer susceptibility genes." (PMID 34461861, 2021). "In addition, CHEK2*1100delC heterozygosity is related to increased risk for several neoplasms such as breast cancer." (PMID 33946049, 2021). "Whether CHEK2 mutations could be associated with early-onset breast cancer should be further investigated." (PMID 35127508, 2021). "CHEK2 mutations are known to increase the risk of prostate and breast cancer." (PMID 33670479, 2021). "Moreover, the mean age at primary breast cancer diagnosis for CHEK2 carriers of truncating variants (excluding carriers of large genomic rearrangements) and CHEK2 carriers of missense variants was 43.88 years [6.83] and 40.12 years [5.8], respectively." (PMID 33925588, 2021). "All patients carrying a pathogenic CHEK2 or RAD51C variant had breast cancer." (PMID 34680878, 2021). "Despite a growing recognition of the role of rare missense variants in cancer predisposition, especially in breast cancer and for genes such as CHEK2 and ATM, missense variants individually are currently most commonly classified clinically as variants of uncertain significance." (PMID 33804961, 2021). "The association of CHEK2 PGVs with moderate risk breast cancer predisposition is well recognized." (PMID 34113003, 2021). "However, in one Polish study of 7494 breast cancer patients and 4346 controls, a CHEK2 pathogenic variant was detected in 3% of women with breast cancer and 0.8% of women in the control group." (PMID 33507482, 2021). "In gene panel sequencing for breast cancer predisposition, CHEK2 is consistently found to have a high number of pathogenic variants, usually only surpassed by the number of pathogenic variants identified in BRCA1 and BRCA2 in most settings not involving selection by breast cancer subtype." (PMID 33803639, 2021). "CHEK2 is considered a moderate risk breast cancer gene, with estimates of the relative risk for women carrying a single pathogenic variant (PV) ranging from 2.0 to 4.8 for a first breast cancer." (PMID 31993860, 2020). "A more precise estimate of individual breast cancer risks associated with germline CHEK2 mutations could be reached by considering the polygenic risk score (PRS)." (PMID 33322746, 2020). "Most studies of CHEK2 germline mutations have dealt with breast cancer patients." (PMID 33322746, 2020).
breast cancer (continued). "As ovarian cancer associates with breast cancer, the patients are analyzed by overlapping or identical NGS panels and thus ovarian cancer patients probably represent the largest cancer group explored for mutations in the CHEK2 gene just after breast cancer patients." (PMID 33322746, 2020). "In addition, germline mutations in DNA damage repair genes such as ATM and CHEK2 are also associated with an increased risk of breast cancer." (PMID 32091409, 2020). "That PRS modifies the risk in PALB2 and CHEK2 mutation carriers supports previous findings suggesting that common genetic variation at least partly explains the widely observed incomplete penetrance of mutations in breast cancer susceptibility genes." (PMID 33318493, 2020). "Interestingly, mutations of CHEK2 have been associated with resistance to anthracycline-based chemotherapy in patients with breast cancer." (PMID 32570972, 2020). "An interesting report by Zhao and colleagues described a Chinese family with the germline CHEK2 mutation c.417A>C (p.Y139*; described independently as a recurrent germline mutation in Chinese breast cancer patients) segregating in all four first-degree relatives with papillary thyroid cancer." (PMID 33322746, 2020). "Both PALB2 and CHEK2 conferred considerably elevated risk for breast cancer." (PMID 33318493, 2020). "The lifetime risk of breast cancer in females with a single pathogenic CHEK2 variant is 25–39%." (PMID 32570972, 2020). "Moreover, since many of the recruited high risk patients tested negative for BRCA1/2 mutations, it is plausible to take advantage of the collected DNA samples and test for mutations in other breast cancer susceptibility genes, e.g. CHEK2, PALB2 and BRIP1." (PMID 29409476, 2018). "Patients with CHEK2 mutations have a greater-than-25% risk of breast cancer." (PMID 29678143, 2018). "The increased risk of breast cancer in patients with CHEK2 mutation is supported by many studies." (PMID 29682443, 2018). "Arguably, CHEK2 is one of the most important breast cancer susceptibility genes after BRCA1/BRCA2." (PMID 30257646, 2018). "In a similar way, the reported breast cancer risk for CHEK2 mutations varies largely." (PMID 29271107, 2018). "Specific atypical associations observed in this analysis were heterogeneous, and numbers were small, but some patterns were noted; for example, 5/16 (31.2%) carriers of CHEK2 variants had been previously diagnosed with renal cell carcinoma (RCC) (breast cancer occurred in 8/16 [50%])." (PMID 29909963, 2018). "BRCA1, BRCA2 and CHEK2 are known breast cancer predisposition genes." (PMID 29678143, 2018). "Missense mutations in CHEK2 confer a 1.4 fold increase in breast cancer risk." (PMID 28265306, 2017). "The same COGS SNP was found in LD with CHEK2, a known breast cancer-associated gene." (PMID 28569218, 2017). "Therefore, we analyzed any CHEK2 mutation as well asassociation between these mutations and breast cancer in Iranian women." (PMID 28680382, 2017). "The homozygotes of CHEK2 mutation are at higher risk of breast cancer development than heterozygote which could explain increased BCR in both general population and daughters of consanguineous parents." (PMID 29157216, 2017).
breast cancer (continued). "Obviously, a similar type of study with a higher number of samples could be useful to show the possible increase in frequency of CHEK2 mutation and may lead to faster diagnosis of patients with breast cancer." (PMID 28680382, 2017). "This CHEK2 variant was also found as somatically mutated in breast cancer in our database." (PMID 28569218, 2017). "Mutations in CHEK2 are known risk factors for female breast cancer." (PMID 28874143, 2017). "In the event the CHEK2 gene mutation had been classified as deleterious, there is a twofold increase in lifetime breast cancer risk, but the level of risk for other associated cancers such as colon, ovarian, kidney, and thyroid is unknown." (PMID 29225998, 2016). "P.I157T is a CHEK2 missense mutation associated with a modest increase in breast cancer risk." (PMID 27716369, 2016). "Additionally, dozens of rare CHEK2 missense mutations have been found in breast cancer patients, but their contribution to disease risk is minor on a population level and causative role in disease development probably varies greatly." (PMID 27716369, 2016). "The associations are even stronger when only specific-cancer genes are considered: all specific-cancer genes in the DSBR class are associated with estrogen-related tissues (CHEK2, breast cancer; RAD51C and RAD51D, ovary cancer; and the DSBR cancer gene BRCA1, breast and ovary)." (PMID 26856619, 2016). "Checkpoint kinase 2 (CHEK2) is a moderate penetrance breast cancer risk gene." (PMID 27716369, 2016). "Also, a larger 5395 bp germline deletion observed in individuals of Eastern European descent, has been linked to increased risk of breast cancer, and recently several germline truncating CHEK2 mutations were linked to risk of Non-Hodgkin Lymphoma." (PMID 27708748, 2016). "This mutation impairs CHEK2 activity and is associated with increased breast cancer risk." (PMID 27484185, 2016). "The results of this study suggest that CHEK2 mutations are rare among high-risk breast cancer patients and may play a minor contributing role in breast carcinogenesis among Malaysian population." (PMID 25629968, 2015). "Numerous studies have demonstrated that CHEK2 is a moderate breast cancer susceptibility gene." (PMID 25884806, 2015). "In addition, the c.1100delC mutation in CHEK2 has been identified as a susceptibility allele with incomplete penetrance and is associated with moderate lifetime risks of breast cancer." (PMID 26577449, 2015). "The CHEK2 c.1100delC allele contributes to a moderate increased breast cancer risk." (PMID 26577449, 2015). "We specifically compared the genomic and gene expression profiles of CHEK2*1100delC breast cancers (n = 14) with BRCAX (familial non-BRCA1/BRCA2/CHEK2*1100delC mutated) breast cancers (n = 34) of the luminal intrinsic subtypes for which both SNP-array and gene expression data is available." (PMID 26553136, 2015). "Since its discovery as a BC susceptibility allele, the occurrence of CHEK2 1100delC mutation depends on the geographical area and/or ethnical characteristics of populations (CHEK2 Breast Cancer Case–control Consortium CHEK2*1100delC and susceptibility to breast cancer 2004)." (PMID 25674498, 2015). "The results of this study suggest that CHEK2 mutations are rare among high-risk breast cancer patients and may play a minor role in genetic predisposition to breast cancer in the Malaysian population." (PMID 25629968, 2015). "In this study, the entire coding sequence of the CHEK2 gene was screened for mutation on 59 breast cancer patients who were non-BRCA1 and BRCA2 mutation carriers and two previously reported missense mutations, p.I160M and p.R180C were identified in two unrelated breast cancer patients." (PMID 25629968, 2015). "The role of CHEK2 in DNA repair by homologous recombination suggests that CHEK2-associated breast cancer (BC) patients might be more sensitive to chemotherapy inducing double-strand DNA breaks, but results hereon are lacking." (PMID 25958056, 2015).
breast cancer (continued). "CHEK2 H371Y confers a 2.43-fold increase in breast cancer risk in Chinese women." (PMID 25884806, 2015). "Thus, the absence or rarity of the CHEK2*1100delC heterozygosity among patients with breast cancer in our population underlines the importance of considering ethnic background before offering a genetic test." (PMID 25674498, 2015). "In addition, four other CHEK2 variants have been associated with increased breast cancer risks including the missense mutations p.I157T and p.S428F, the splice site mutation IVS2 + 1G > A and the large genomic deletion del5395." (PMID 25629968, 2015). "The purpose of this study was to investigate whether breast cancer patients with CHEK2 H371Y mutation were more likely to respond to neoadjuvant chemotherapy." (PMID 25884806, 2015). "The Consortium found the frequency of CHEK2 1100delC to be 1.9% and 0.7% in cases and controls respectively, and confirmed that this gene variant could potentially increase the risk of breast cancer." (PMID 25674498, 2015). "However, it is possible that other CHEK2 variants will confer susceptibility to breast cancer in other countries." (PMID 25674498, 2015). "CHEK2*1100delC is a moderate-risk breast cancer susceptibility allele with a relatively high prevalence in the Netherlands of 1.1 % in the general population, 2.5 % in unselected breast cancer cases, and 4.9 % in familial breast cancer cases." (PMID 26553136, 2015). "Notably, both Indian cases carrying the p.I160M variant were diagnosed with breast cancer at the age >45 while all four CHEK2 p.R180C carriers were diagnosed with breast cancer at the age of ≤45." (PMID 25629968, 2015). "Germline mutations in CHEK2 gene have been associated with increase in breast cancer risk." (PMID 25629968, 2015). "The CHEK2 gene has been proposed as a moderate penetrance breast cancer susceptibility gene." (PMID 25629968, 2015). "In 2004, CHEK2-Breast Cancer Consortium did a collaborative analysis with 10 studies from 5 western countries, which involved 10 860 breast cancer cases and 9 065 controls (CHEK2 Breast Cancer Case–control Consortium CHEK2*1100delC and susceptibility to breast cancer 2004)." (PMID 25674498, 2015). "For instance, CHEK2 1100delC mutation was frequently observed in some Western and Northern Europe (CHEK2 Breast Cancer Case–control Consortium CHEK2*1100delC and susceptibility to breast cancer 2004), but it was very rare in the Central Europe, Southern Europe (Italy and Spain) and Australia." (PMID 25674498, 2015). "Germline mutations of the CHEK2 gene have been reported to be associated with breast cancer." (PMID 24713400, 2014). "Obtained results suggest that CHEK2 mutations could potentially contribute to the susceptibility to breast cancer." (PMID 24713400, 2014). "Constitutional mutations of CHEK2 predispose to many types of common cancers, e.g. breast cancer." (PMID 24713400, 2014). "Thus far, five deleterious recurrent mutations in CHEK2 have been identified that confer about twofold elevated risk of breast cancer in unselected female population." (PMID 23806170, 2013). "In a study conducted in China that looked at CHEK2 mutations based on whole gene analysis, a novel recurrent missense mutation, p.H371Y, was identified in 5/118 (4.2%) familial and 16/909 (1.8%) unselected breast cancer patients and in 9/1,228 (0.7%) controls." (PMID 23806170, 2013). "The results of this study and the present one suggest that CHEK2 germ line mutations may contribute to breast cancer susceptibility in populations from East Asia, but may play a minor role in a South Asian population from Pakistan." (PMID 23806170, 2013). "The odds ratio of breast cancer in the presence of a deleterious CHEK2 mutation was 5.18." (PMID 22114986, 2011). "Furthermore, we observed that the CHEK2 1100delC gene-expression signature is related to increased risk of breast cancer relapse." (PMID 21542898, 2011).
breast cancer (continued). "CHEK2 (checkpoint kinase 2) is an intermediate-level breast cancer risk gene, whose truncating mutation 1100delC doubles the risk of unselected women, but gives rise to much higher risk for women who have a family history of breast cancer." (PMID 21542898, 2011). "Germline CHEK2 mutations are associated with breast cancer in different populations." (PMID 22114986, 2011). "On the one hand, these numbers could be an underestimate because CHEK2 might be among the most important (in terms of familial relative risk) of the intermediate-risk class of breast cancer susceptibility genes." (PMID 21244692, 2011). "In order to fully assess the contribution of CHEK2 in breast cancer susceptibility, we aimed to test whether the gene was subject to differential allelic expression (DAE)." (PMID 21569354, 2011). "Loss of 22q, where the CHEK2 locus resides, is a common event in breast cancer." (PMID 21542898, 2011). "We further tested whether the 188 CHEK2 1100delC-related genes might be associated with breast cancer prognosis." (PMID 21542898, 2011). "Our work indicates that a variety of deleterious CHEK2 alleles make an appreciable contribution to breast cancer susceptibility, and their identification could help in the clinical management of patients carrying a CHEK2 mutation." (PMID 22114986, 2011). "However, no large-scale study has used full open reading frame mutation screening to assess the contribution of rare missense substitutions in CHEK2 to breast cancer risk." (PMID 21244692, 2011). "CHEK2 was the first moderate-risk breast cancer gene being identified." (PMID 19607694, 2009). "Given that 70–80% of CHEK2-associated breast cancers are ER-negative, women with a mutation may be a good candidates for tamoxifen chemoprevention." (PMID 19401704, 2009). "We investigated whether the CHEK2*1100delC mutation carrier status increases the risk for asynchronous contralateral breast cancer (CBC) and whether it interacts with radiation therapy (RT) or chemotherapy in regard to CBC risk." (PMID 18253122, 2008). "However, it is unlikely that CHEK2 alleles other than 1100delC significantly influence familial breast cancer risk within our study group." (PMID 18706089, 2008). "We investigated the risk for contralateral breast cancer (CBC) associated with the CHEK2*1100delC germline mutation among approximately 2100 women with breast cancer who were cases and controls in the multicentre Women's Environment, Cancer and Radiation Epidemiology (WECARE) Study." (PMID 18253122, 2008). "Thus, much remains to be studied with respect to CHEK2 alleles in the French Canadians, but it seems unlikely that a specific, common founder mutation for breast cancer exists in this population." (PMID 18706089, 2008). "The truncating mutation, CHEK2*1100delC, seems to increase the risk for breast cancer." (PMID 18253122, 2008). "In addition, we explored the joint effect of being a carrier of mutated CHEK2 and having received RT or chemotherapy for breast cancer." (PMID 18253122, 2008). "Furthermore, a recent publication also showed a strong association (odds ratio (OR) 3.21) between CHEK2*1100delC carrier status, breast cancer risk and a history of chest X-rays." (PMID 17428320, 2007). "In our study CHEK2 1100delC was associated with familial breast cancer (2.2% vs. 0.7% in controls, p = 0.03) and confirm previous results of the variant as a risk factor for breast cancer." (PMID 17705858, 2007). "One group found a relationship between poor breast cancer prognosis and common haplotypes in the ERBB2 gene, but to our knowledge, nothing has been reported regarding the association between common haplotypes in the ATM and CHEK2 genes and breast cancer survival or tumour characteristics." (PMID 17132159, 2006).